HGF (hepatocyte growth factor)
Diseases named in the same sentence as HGF in open-access papers (continued):
Sharing a sentence is not in itself a finding about the gene and the disease.
prostate carcinoma (continued). "To further assess the cellular activity of HVS against c-Met, we next measured its effect on c-Met phosphorylation in DU145 prostate cancer model, which responds well to HGF stimulation." (PMID 27086914, 2016). "It has been well documented that DU145 prostate cancer cells, which normally grow in clusters, exhibit a disruption and scattering of the cell colonies upon HGF stimulation." (PMID 27086914, 2016). "The phosphorylation levels of Akt and ERK were determined in DU145 prostate cancer cell lysates after treating cells with various concentrations of HVS or S-oleocanthal for 30 min followed by HGF stimulation before cell lysis." (PMID 27086914, 2016). "Prior studies have documented enhancement of this phosphorylation and localization to the focal adhesion complexes, following addition of HGF in prostate cancer cells." (PMID 26052252, 2015). "Our results clearly indicate that levels of HGF induced phosphorylation were significantly reduced in prostate cancer cells following elimination of WAVE-3 along with reduced motility and invasion." (PMID 26052252, 2015). "This study examined the effect of WAVE-3 on the HGF induced migration and invasion of prostate cancer cells." (PMID 26052252, 2015). "HGF (human growth factor)-driven prostate cancer cell migration involved activation of PAK4–LIMK1 pathway." (PMID 27919028, 2014). "We report here that PAK6 is specifically required for carcinoma cell–cell dissociation downstream of hepatocyte growth factor (HGF) for both DU145 prostate cancer and HT29 colon cancer cells." (PMID 24352566, 2014). "It is well established that HGF can induce cell–cell dissociation and that HGF signaling plays a role in prostate cancer metastasis." (PMID 24352566, 2014). "We have previously shown that the plant polyphenols EGCG and luteolin are able to inhibit breast and prostate carcinoma cell motility and invasion stimulated by the growth factor, HGF, in vitro." (PMID 25272043, 2014). "In this study, as previously published, prostate cancer cells were serum starved and treated with HGF 24 h prior to all assays, to promote cell migration." (PMID 24795148, 2014). "The aberrant expression of HGF (hepatocyte growth factor) and its receptor, c-Met, often correlate with advanced prostate cancer stages." (PMID 22848758, 2012). "Our data are in line with these results, demonstrating that stimulation of more mature prostate cancer cells with HGF can induce a stem-like marker profile and high tumour-formation in vivo." (PMID 22110593, 2011). "Despite the limited availability of c-MET models in prostate cancer, these results indicate that HGF-mediated induction of a stem-like phenotype is representative for human disease." (PMID 22110593, 2011). "Our objective is to determine the role of immature cells in prostate cancer by analysis of the HGF/c-MET pathway." (PMID 22110593, 2011). "Aberrant expression of HGF/SF and its receptor, c-Met, often correlates with advanced prostate cancer." (PMID 20946682, 2010). "While DU145 prostate cancer cells exhibited a longer c-Met activation in response to HGF, in both DU145 and AGS cells H. pylori-induced phosphorylation of the 125 kD protein in a much more sustained fashion." (PMID 19439912, 2009). "We searched for Met or any HGF binding partner on the cells of the PC3 and LNCaP prostate cancer cell models, using HGF immobilized on agarose beads." (PMID 16869958, 2006). "Membrane localized nucleolin binds heparin-bound growth factors (including HGF) and appears upregulated during prostate cancer progression." (PMID 16869958, 2006). "We have found evidence that HGF secreted by prostate stromal cells regulates prostate cancer cell adhesive behaviors, even in cells that lack Met, the one known HGF receptor." (PMID 16869958, 2006).
prostate carcinoma (continued). "C4-2, an LNCaP lineage-derived, androgen-independent human prostate cancer cell line, responds to HGF in a concentration-dependent manner by increasing its adhesion and reducing its migration on laminin substratum." (PMID 16869958, 2006). "The integrin acts upstream of MET in an HGF-independent manner such that treating or plating ovarian, breast, lung or prostate cancer cells with or on integrin substrates, such as fibronectin, collagen or laminin, triggers MET phosphorylation in various cell models." (PMID 40138447, 2025). "Finally, traditionally considered a paracrine factor, HGF’s autocrine role is increasingly being highlighted in several cancers, including acute myeloid leukemia, prostate cancer, lymphoma, and glioblastoma." (PMID 38212428, 2024). "By activating FYN, HGF/MET promotes the progression of prostate cancer." (PMID 36740671, 2023). "Other results showed a substantial decrease in serum levels of prostate-specific antigen (PSA), vascular endothelial growth factor (VEGF) and hepatocyte growth factor (HGF) in men with prostate cancer after short-term treatment with EGCG (Polyphenon E), with no raise in liver enzymes." (PMID 37239974, 2023). "Furthermore, TMPRSS2 has been shown to activate the single-chain precursor of hepatocyte growth factor (HGF), which contributes to prostate cancer metastasis." (PMID 35163273, 2022). "This was illustrated by the changes in HGF-mediated signalling made possible via the catenin complex and affecting changes in the barrier function and, hence, increases in aggressive phenotypes of human prostate cancer cell lines." (PMID 35204839, 2022). "Therefore, TPX2 enhanced the activation of the HGF/ETS-1 pathway to enhance the invasion of endocrine-independent prostate carcinoma cells and thus it would be a promising target for prostate carcinoma treatment." (PMID 34123781, 2021). "Another report revealed that the HGF/ETS pathway could be active in the TCGA molecular subgroup of TMPRSS2/ERG fused prostate cancers (50%)." (PMID 34123781, 2021). "Knockdown of SIPA1 silenced the effect of HGF on TJs in breast and prostate cancer cells." (PMID 33917539, 2021). "Interestingly, FYN has been shown to be an important effector in the HGF/MET signaling axis that acts as a crucial oncoprotein in prostate cancer metastasis." (PMID 32811808, 2020). "Other studies have suggested that c-met, the receptor of hepatocyte growth factor, could represent a marker of immature prostate cancer cells." (PMID 31366128, 2019). "The main aims of the study were to assess the circulating level of leptin and omentin as well as related proteins: HGF and VEGF in men with prostate cancer and benign prostate hyperplasia, and to study the associations between their concentrations and PSA level." (PMID 30186533, 2018). "It allows to use HGF as a potential indirect prostate cancer biomarker." (PMID 30186533, 2018). "It was found that prostate cancer stem-like cells (CSCs)/cancer initiating cells (CICs) express hepatocyte growth factor (HGF) and that the HGF/c-MET proto-oncogene product (c-MET) signal has a role in the maintenance of prostate CSCs/CICs in an autocrine fashion." (PMID 27447616, 2016). "Overall, HVS proved a robust inhibitor of HGF-induced scattering in DU145 prostate cancer cells." (PMID 27086914, 2016). "HGF can increase both invasion and haptotactic migration of prostate cancer cells." (PMID 26052252, 2015). "HGF derived from prostate stroma, promotes proliferation, differentiation, motility, and invasion of malignant epithelial cells indicating possible involvement in the progression of prostate cancer." (PMID 26052252, 2015). "Although EMT induced by HGF has been investigated in various types of cancer, the tumorigenic association between EMT and c-Met, particularly in prostate cancer, remains unclear." (PMID 25202379, 2014).
prostate carcinoma (continued). "Given that HGF and VEGF are secreted from surrounding tumor myofibroblasts, these observations suggested that EGCG may inhibit prostate cancer-associated myofibroblast differentiation." (PMID 25272043, 2014). "Moreover, Fyn is located downstream of the HGF/Met signaling pathway and impacts cellular tropism and shape in prostate cancer cell line." (PMID 25594017, 2014). "Preclinical studies have shown that BMS-777607 delays the growth of human gastric cancer xenografts with MET gene amplification, inhibits HGF-induced metastasis-related functions in prostate cancer cells, and impairs pulmonary metastases in a rodent sarcoma model with hyperactivated c-Met." (PMID 22639908, 2012). "Furthermore, the human c-MET receptor in prostate cancer xenografts has low sensitivity for murine HGF, so that external human HGF sources or transgenic mice are required for functional HGF/c-MET analysis." (PMID 22110593, 2011). "Interaction of HGF with its receptor has been demonstrated to modulate cell proliferation, tumor cell interaction, cell migration, cell-matrix adhesion, cell invasion, and angiogenesis in prostate cancer cells." (PMID 21949592, 2011). "We identified that fetal bovine serum, some growth factors (epidermal growth factor, androgen, insulin-like growth factor-I, and hepatocyte growth factor) and cytokines (TNFα and interleukin-1beta) induced midkine expression in a human prostate cancer cell line LNCaP cells." (PMID 18275606, 2008). "The findings we report here, together with the nucleolin-focused independent clinical trial underway, introduce nucleolin as an attractive target for therapeutic regulation of prostate cancer, although the details of its position in cancer cell HGF signaling remain to be found." (PMID 16869958, 2006). "Thus, although both HGF and Met are arguably very important for prostate cancer progression, the details of their functions remain far from clear." (PMID 16869958, 2006). "Further, we report that the nucleolin protein expressed on the surfaces of these prostate cancer cells (in increasing levels during disease progression) is involved in the HGF regulatory interplay between stromal and epithelial cells within the prostate, and possibly also at sites of metastasis." (PMID 16869958, 2006). "For example, high-Met-expressing DU145 prostate cancer cells showed concentration-dependent responses to HGF, with increased cell motility in both scatter and invasion assays, whereas PC3 cells (with equally high levels of Met expression) did not respond under the same conditions." (PMID 16869958, 2006). "In prostate CAFs, TRPA1 could be activated by the natural polyphenolic antioxidant, resveratrol, and induced the secretion of VEGF and hepatocyte growth factor (HGF), which in turn reduced resveratrol-induced apoptosis in co-cultured human prostate cancer cells." (PMID 37174661, 2023). "And HGF-MET may be the dominant mechanism mediating EMT in prostate cancer cell lines." (PMID 31867280, 2019). "Similarly, agents targeting HGF in prostate cancer are in different phases of clinical trial." (PMID 28117763, 2017). "It has been demonstrated that HGF could impact the metastasis of prostate cancer." (PMID 27547510, 2016). "Thus, HVS blocked HGF-driven growth not only in two-dimensional (2D) cultures but also in 3D spheroid systems, suggesting its potential for the control of c-Met-dependent solid tumors, including breast and prostate cancers." (PMID 27086914, 2016). "Although prostate cancer PC-3 cells are responsive to exogenous HGF, our previous study showed that these cells exhibit a high basal level of autophosphorylated c-Met, suggesting that c-Met could be constitutively activated even in the absence of exogenous HGF." (PMID 22639908, 2012).
prostate carcinoma (continued). "In prostate cancer, serum HGF has been identified as an independent prognostic factor for advanced disease and c-Met expression in metastatic lesions frequently exceeds that of primary tumors, with positive expression reported in more than 90% of prostate cancer bone metastases." (PMID 22639908, 2012). "A study in prostate cancer CAFs identified that TRPA1 activation by resveratrol leads to strong Ca2+ cytosolic influx and secretion of VEGF and HGF." (PMID 40640495, 2025). "According to Hsieh and Wu’s 2020 research, RES inhibited the release of hepatocyte growth factor (HGF) by stromal cells, which in turn impedes invasion and the epithelial–mesenchymal transition (EMT) in prostate cancer (PCa) cells." (PMID 40143065, 2025). "In our study, we found a positive correlation between the expression of both MET and HGF and the expression of FOXP2 in prostate cancer tissues, FOXP2-overexpressing human prostate epithelial cells RWPE-1, and FOXP2-overexpressing NIH3T3 cells." (PMID 37668356, 2023). "Almost all patients demonstrated a rapid increase in plasma HGF, reaching peak levels of POD1 in breast and colorectal cancer patients and POD3 in prostate cancer patients, consistent with other reports." (PMID 38067195, 2023). "Treatment with tea polyphenol, epigallocatechin-3-gallate (EGCG), decreases the serum levels of HGF and VEGF in prostate cancer patients." (PMID 37065872, 2023). "We observed a rapid and significant rise in HGF levels after surgery, reaching maximal levels on postoperative day (POD) 1 for breast and colorectal cancer patients and on POD3 for prostate cancer patients." (PMID 38067195, 2023). "Since HGF and VEGF are mostly secreted by stromal myofibroblasts in the tumor microenvironment, EGCG can prevent myofibroblast differentiation in prostate cancer." (PMID 37065872, 2023). "Conversely, the core members (HGF, MET, and PIK3CA) were downregulated in the FOXP2 knockdown PC3 prostate cancer cells." (PMID 37668356, 2023). "Heteronemin efficiently inhibited the HGF-stimulated c-Met/STAT3 in prostate cancer cells and also suppressed HGF-induced colony formation." (PMID 35705962, 2022). "Pathway analysis of CD45+ TAS and CD45+ tumor epithelium differential expression revealed a number of prostate cancer related pathways including epithelial adherent molecules junction signaling, TEC kinase signaling, and HGF." (PMID 36230846, 2022). "In prostate cancer, TMPRSS2 activated pro-hepatocyte growth factor (HGF) and then promoted c-MET receptor tyrosine kinase signaling to regulate cell carcinogenesis." (PMID 35558557, 2022). "Of note, this same study also noticed that RSV can exert an opposite effect on cells expressing a mutant TRPA1, which not only increased expression and secretion of HGF and VEGF, but also enhanced prostate cancer metastasis." (PMID 33535458, 2021). "An in vitro study that focused on the interactions between prostate cancer cells and CAFs identified that resveratrol activates the TRPA1 calcium channel in CAFs and leads to a strong Ca2+ influx and secretion of VEGF and HGF." (PMID 34768796, 2021). "Hepatocyte growth factor is found in the prostate tumor microenvironment; it triggers invasion, metastasis, and EMT, and induces NHE activity in DU 145 prostate cancer cells." (PMID 34948058, 2021). "Various factors, such as hepatocyte growth factor (HGF) and epidermal growth factor (EGF) that are altered in the prostate cancer microenvironment through increased production by tumor cells or the cancer-associated stroma are candidates for eliciting EMT." (PMID 34831167, 2021). "Hepatocyte growth factor is found in the prostate tumor microenvironment; it triggers invasion, metastasis, and EMT, and also induces NHE activity in DU 145 prostate cancer cells." (PMID 34948058, 2021).
prostate carcinoma (continued). "In prostate cancer survivors with history of radiation therapy, elevated levels of PAI 1, TIMP1, TIMP2, HGF and VEGF-A were detected in patients that received a radiation cystitis diagnosis." (PMID 33119677, 2020). "It efficiently antagonizes hepatocyte growth factor (HGF)-stimulated c-Met/STAT3 activation, and the proliferation and colony formation of refractory prostate cancer cells." (PMID 32630719, 2020). "Cell viability of prostate cancer cells was determined after separate and combined treatment with EVO and HGF." (PMID 32183146, 2020). "HGF is a potent agonist of tumor progression and invasiveness, and PAK4 is required for HGF-induced progression and invasion of human prostate cancer cells." (PMID 30755582, 2019). "It efficiently antagonizes the hepatocyte growth factor (HGF)-stimulated c-Met/STAT3 activation, as well as proliferation and colony formation in refractory prostate cancer cells." (PMID 30563284, 2018). "In prostate cancer patients, tea polyphenols are known to suppress serum levels of PSA, VEGF, and hepatocyte growth factor (HGF)." (PMID 30319623, 2018). "Signaling through both the HGF/c-Met and EGF/EGFR is a potent inducer of cell scattering in the DU145 prostate cancer cell line." (PMID 28978320, 2017). "In one study, the effect of hepatocyte growth factor (HGF) on TJ function in human prostate epithelial, prostate stem cell-like and prostate cancer cell lines was evaluated." (PMID 27547510, 2016). "While many groups have studied the role of HGF/MET signaling in epithelial-mesenchymal transition, little is known of the actual role of this pathway in clinical prostate cancer." (PMID 27105539, 2016). "BMP co-receptor repulsive guidance molecule b (RGMb) was upregulated in vascular endothelial cells after hepatocyte growth factor (HGF) stimulation, which was combined with BMP-7 to induce angiogenesis in breast and prostate cancers." (PMID 27661009, 2016). "HGF, and its cell surface receptor (aka MET kinase), are well described in progression and invasion of several tumor types, including prostate cancer." (PMID 27599544, 2016). "The serum levels of HGF and PSA are found to be significantly increased in prostate cancer patients." (PMID 26052252, 2015). "In our presented study, TGFβ-bearing prostate cancer exosomes modulated the differentiation of BM-MSC, giving rise to a myofibroblastic phenotype exhibiting heightened VEGF and HGF secretion." (PMID 25596732, 2015). "We have previously shown that (−)-Epigallocatechin-3-gallate (EGCG), in the form of Polyphenon E, significantly decreases serum levels of HGF and VEGF in prostate cancer patients." (PMID 25272043, 2014). "Hepatocyte growth factor (HGF) is well known to elicit such a cell scattering response in a number of different cell lines, including prostate carcinoma DU145 cells." (PMID 24352566, 2014). "In conclusion, activation of the HGF/c-MET pathway gives rise to a stem-like phenotype, preferentially at the invasive front of human prostate cancer." (PMID 22110593, 2011). "To explore the molecular pathways relevant for c-MET function in prostate cancer, we performed microarray expression analysis of DU145 cells stimulated with HGF." (PMID 22110593, 2011). "To determine if this result was cell-specific, and to address HGF-mediated signaling in shMET cells, we generated DU145 prostate cancer cells that stably express the shRNAs targeting c-Met (shMET)." (PMID 19439912, 2009). "Cell spreading responses to HGF are concentration-dependent for both PC3 and C4-2 prostate cancer cell lines, but an effective dose 50 (EC50) for PC3 cells is achieved at a lower concentration (5 ng/ml) than for C4-2 cells (30 ng/ml)." (PMID 16869958, 2006). "In addition, immune and inflammation-related pathways were prominent, including IL-6 signaling (in breast and prostate cancer) and Hedgehog/IGF/HGF cooperation in stem cell regulation, suggesting acquisition of cancer stemness traits." (PMID 41399370, 2026).